RN7SKP122 (RN7SK pseudogene 122)
Gene: Miscellaneous RNA gene on chromosome 5 (107,810,629 to 107,810,924, forward strand). Ensembl gene ENSG00000251732.
Homologues: Orthologues: chimpanzee 7SK (96% identical), mouse Gm54538 (44% identical). Paralogues in human: RN7SKP226 (56% identical), RN7SKP45 (56% identical), RN7SKP87 (56% identical), 7SK (56% identical), RN7SKP130 (55% identical), RN7SKP246 (55% identical), RN7SKP25 (55% identical), RN7SKP250 (55% identical), RN7SKP37 (55% identical), RN7SKP4 (55% identical), RN7SKP269 (55% identical), RN7SKP150 (55% identical), and 284 more.